IRF5 (interferon regulatory factor 5)
Diseases named in the same sentence as IRF5 in open-access papers (continued):
Sharing a sentence is not in itself a finding about the gene and the disease.
Zinc deficiency (1 paper, 2020). A deficiency of the essential metal Zinc; an essential cofactor for many enzymes. "Finally, the nuclear distribution of interferon regulatory factor 5 (IRF5), an important transcriptional factor for IL-23p19, induced by zinc deficiency enhanced IL-23p19 expression in TPEN-treated BMDMs." (PMID 32331308, 2020).
tumor (127 papers, 2009 to 2026). "Targeted mRNA nanocarriers encoding IRF5 and IKKβ can effectively reprogram TAMs from an immunosuppressive M2 phenotype to a pro-inflammatory M1 phenotype, thereby promoting an anti-tumor immune response." (PMID 40330466, 2025). "IRF5 has been shown to possess a multitude of functions, such as activating genes that encode inflammatory cytokines, type I interferons, and tumor suppressors." (PMID 40529613, 2025). "IRF5 therapy has previously been found to increase the proportion of proinflammatory monocytes and decrease the abundance of immunosuppressive tumor‐associated macrophages." (PMID 40971720, 2025). "A nanoparticles-based delivery of mRNAs encoding interferon regulatory factor 5 and its activating kinase IKKβ promisingly reprogram TAMs into M1-like phenotype, consequently inducing anti-tumor immunity and promoting tumor regression in vitro." (PMID 37012233, 2023). "To understand the underlying mechanisms of IRF5/ IKKβ NP-mediated anti-tumor effects, we first examined how exclusively mannose receptor-targeting confined NP interaction to phagocytes." (PMID 31481662, 2019). "Receptor recognition of these tumor cells causes the activation of the IRF5 transcription factor and downstream gene induction for the full-blown tumoricidal activity of NK cells." (PMID 25149452, 2014). "Consistent with this, we show exacerbated in vivo tumor growth in mice genetically deficient in either Dectin-1 or IRF5." (PMID 25149452, 2014). "Certainly, if there an elevated proportion of patients have metastases showing loss of heterozygosity the “A” allele at IRF5, then this would imply that the IRF5 genotype of the tumor itself is important." (PMID 22909381, 2012). "Data presented here support a unique role for IRF5 in regulating mammary epithelial cell growth and provide the first direct evidence that loss of IRF5 tumor suppressor function contributes to breast tumorigenesis." (PMID 22053985, 2011). "In this study, we have characterized a mutated form of IRF-5 in tumor or transformed B and T cell lines and in PBMCs derived from patients suffering from ATL or CLL." (PMID 19430534, 2009). "In addition, we also determined that known downstream signaling molecules activated by interferon-gamma receptors associated with macrophages, namely STAT1, IRF1, and IRF5, were also correlated with poor OS outcomes in tumor samples." (PMID 38539537, 2024). "Moreover, direct relationships between loss of IRF5 expression and accelerated tumor initiation and growth, increased metastatic burden, and worsened overall prognosis have been reported." (PMID 38969706, 2024). "IRF5/CSF activation facilitates tumor-associated M2 expression, and IRF7 induces PD-L1 production." (PMID 39384770, 2024). "Furthermore, we discovered that overexpressing HLA‐E can counteract the tumor‐promoting effects of IRF5‐deficient M1‐like macrophage exosomes." (PMID 39623605, 2024). "Delivery of a targeted nanocarrier formulated with IVT mRNA encoding IRF5 and IKKβ, induced reversion of the suppressive state of TAMs from a tumor-supporting phenotype towards a phenotype that induced anti-tumor immunity and promoted tumor suppression." (PMID 33658037, 2021). "By encoding IRF5 together with its activating kinase IKKβ, TAMs were reprogrammed to trigger anti-tumor response and facilitated tumor cell death after infused of nanoparticles formulated with mRNAs to reverse their immunosuppressive, tumor-supporting state." (PMID 34368156, 2021). "Clinical data from tissue specimens combined with expression analyses and 3-D cultures provide the first clues that IRF5 may be involved in regulating tumor metastases, where loss of IRF5 enhances metastatic potential." (PMID 22053985, 2011). "Finally, assessment of gene expression in relation to 14 tumour states revealed that IRF5 function may be associated with anti‐apoptosis, epithelial‐mesenchymal transition (EMT) and inflammatory response." (PMID 39993973, 2025).
tumor (continued). "mRNA array results of colon 38 tumor following CPT-11+YIV-906 treatment suggested that YIV-906 could switch the immune status of tumor from chronic to acute inflammation associated with the up-regulation of IRF5, IFN, and JAK/STAT signaling." (PMID 30510512, 2018). "IRF-5 function has been studied in detail in antigen presenting cells and tumor cells, where it regulates the inflammatory and anti-viral response, macrophage polarization, cell cycle, and cell death." (PMID 40494997, 2025). "Although our study primarily focuses on tumor-intrinsic IRF5 functions, future investigations should explore ISL’s impact on the immune compartment of the TME, potentially enhancing antitumor immunity through immune cells." (PMID 41179282, 2025). "The study of IRF1 and IFN-β roles in M1 polarization of macrophages and their anti-tumor functions demonstrated that these two factors regulate IRF5 expression, contributing to M1 polarization." (PMID 39941858, 2025). "Spearman correlation analysis revealed that IRF5 was positively correlated with tumour cells, DC cells, and B cells and negatively correlated with epithelial cells and fibroblasts." (PMID 39993973, 2025). "In murine models of ovarian cancer, melanoma, and glioblastoma, the IRF5/IKKβ NPs localized within tumor sites, where they reprogrammed TAMs, reduced M2 macrophage presence, and increased inflammatory cytokine production." (PMID 40330466, 2025). "This indicates that the interplay among IRF1, IFN-β, and IRF5 is crucial for the M1 polarization of macrophages and their anti-tumor activities, providing potential targets for cancer therapy." (PMID 39941858, 2025). "IRF5 plays an important role in pathogen defence and immune cell differentiation and plays tumour‐suppressive and tumour‐promoting roles in different tumours." (PMID 39993973, 2025). "Nanoparticles carrying mRNA encoding interferon regulatory factor 5 (IRF5) and activating kinase IKKβ successfully shifted TAM polarization to anti-tumor states." (PMID 40427130, 2025). "By up-regulating the expression of IRF5 and down-regulating CCL5, it promotes the transformation of M2 tumor-associated macrophages, reprograms the tumor microenvironment immunology, and achieves substantial reduction in postsurgical pancreatic tumor regrowth." (PMID 40868764, 2025). "By downloading TCGA pan‐GI data as well as normal samples from GTEx, we found that IRF5 was highly expressed in pan‐GI tumours; however, when the data were restricted to TCGA only, IRF5 expression was dysregulated only in ESCA." (PMID 39993973, 2025). "Then, the cellular components as well as the spatial localisation of IRF5 were calculated after spatial transcriptomics deconvolution, and it was found that IRF5 was mainly localised to tumour cells, DC cells and B cells." (PMID 39993973, 2025). "IRF5, identified as a tumor suppressor, exhibits down-regulated mRNA and protein expression levels in HCV-infected human hepatocytes and cells with autonomous replication of HCV RNA." (PMID 38999981, 2024). "As a characteristic gene of M1‐type macrophages, IRF5 has been observed to promote polarization towards M1‐type in vitro, affecting the function of M1‐type macrophages and the survival of tumor cells." (PMID 39623605, 2024). "For instance, NK cell-dependent tumour cell clearance relies on Dectin-1 interaction with N-glycan structures of tumour cells through activation of the IRF5 transcription factor and NK-mediated tumour cell killing." (PMID 38668817, 2024). "Here, we identified HLA‐E as a downstream target gene of IRF5 and demonstrated that the overexpression of HLA‐E can counteract the tumor‐promoting effects induced by si‐IRF5 M1‐exos." (PMID 39623605, 2024). "Our model of t-dEVs from IRF5-high and IRF5-low tumor cell lines provides additional pre-clinical evidence for altering the landscape of a tumor microenvironment and its PMN by packaging IRF5 into EV-like nanoparticles for therapeutic delivery." (PMID 38969706, 2024).
tumor (continued). "Genes such as COL1A1, COL1A2, and COL3A1, which are implicated in the tumor microenvironment, and immune-related genes, such as THY1, IRF5, and HLA-DRA, exhibited significant expression level changes." (PMID 38672562, 2024). "The role of IRF5 has been increasingly explored in tumor development and metastasis due to its well-established role as a tumor suppressor in many cancers." (PMID 38969706, 2024). "In the granulocytic subset, there were no major differences, although there was a trend toward an increase in the IRF5 low tumor bearing mice at later stages of PMN development." (PMID 38969706, 2024). "Recent studies have revealed that IRF5 also contributes to tumor occurrence and development by regulating tumor immune escape and promoting antitumor immune response." (PMID 39623605, 2024). "Further research determining the interplay between IRF5 and these proteins in different tumor cells is necessary to elucidate the impact of IRF5 on malignant potential." (PMID 38969706, 2024). "Conversely, tumor tissue retaining the top quartile of IRF5 expression positively correlated with increased overall and recurrence-free survival." (PMID 38969706, 2024). "Taken together, these results suggest that macrophage polarization in the LGG TME can be driven by interferon-gamma activation of the STAT1/IRF1/IRF5 to promote tumor progression in concert with TGFB2 levels." (PMID 38539537, 2024). "Mechanistically, IRF5-positive tumor cells retain IRF5 transcripts within t-dEVs that contribute to altered composition, secretion, and trafficking of t-dEVs to sites of metastasis." (PMID 38969706, 2024). "In vivo, the inhibitory effect of IRF5 M1‐exos on tumor growth was observed by establishing a tumor‐bearing model in nude mice." (PMID 39623605, 2024). "Factors such as IRF5 can actually contribute to the low-grade inflammatory context and increase lactate production, resulting in the most detrimental tumor-supporting mixed M1/M2 phenotype of TAMs." (PMID 39516356, 2024). "The relationship between IDO1 and marker genes of tumor-associated macrophages (TAMs; CCL5, CD68, and IL10), M1 (IRF5, NOS2, and PTGS2), and M2 (CD163, VSIG4, and MS4A4A) macrophages was analyzed." (PMID 39351094, 2024). "Further, much of our focus was on the specific immune programming effects of t-dEVs on the lungs due to the role of IRF5 as a transcription factor that mediates immune activation and recruitment of tumor infiltrating lymphocytes." (PMID 38969706, 2024). "FBXL8 knockdown leads to the accumulation of CCND2 and IRF5 in breast cancer cells and inhibited tumour progression." (PMID 36855778, 2023). "Genetically reprogramming M2 with increased IRF5/IKKβ expression regulated M1 politization for enhanced T cell tumor infiltration." (PMID 36257824, 2022). "This tumor control by eosinophils is driven by the GM-CSF–interferon regulatory factor 5 (IRF5) axis and can be counter regulated by IL-10." (PMID 34572273, 2021). "In support of this, we also found significantly higher levels of IRF5+ cells within tumor sections treated with the α-PD-L1 antibody alone or in combination with CTX." (PMID 34206051, 2021). "In support of this, we also found higher levels of IRF5+ cells within tumor sections treated with the α-PD-L1 antibody alone or in the combination, often co-localized with PD1+ cells." (PMID 34206051, 2021). "Therapeutic responses between fully immunocompetent and lymphocyte-depleted mice were compared after six IRF5/IKKβ NP doses (D27) using bioluminescence tumor imaging." (PMID 31481662, 2019). "It was established through co-culture experiments that certain tumor cells express N-glycan structures, which can bind dectin-1 on macrophages and DCs, resulting in downstream activation of interferon regulatory factor 5 (IRF5)." (PMID 30233579, 2018).
tumor (continued). "IRF5 functions as both an antiviral signaling factor and tumor suppressor by inducing apoptosis in response to viral infection or DNA damage." (PMID 29438328, 2018). "As IRF5 can induce p21, Bak, Bax, and Caspase 8, making it a potential candidate of tumor-suppressor." (PMID 28562332, 2017). "Although less is known about IRF5, it is also lost in certain cancer types, and exogenous IRF5 expression is sufficient to sensitize cells to DNA damage and inhibit tumor growth." (PMID 27809273, 2016). "For example, anti-tumor function of IRF-1- and IRF-5-associated pathways have been suggested in CRC." (PMID 27092172, 2016). "To examine the contribution of immune cells, we next conducted bone marrow transplantation and found that IRF5 expression specifically in bone marrow-derived cells critically contributes to the suppression of the tumor cell metastasis." (PMID 25149452, 2014). "Activation of wild type IRF5 typically results in tumor suppressive and antiviral activities, however, EBV specific induction of a dominant negative IRF5 indicates that the virus is capable of inhibiting the anti-viral effects of cellular IRF5." (PMID 23061052, 2012). "This, combined with in vitro data suggesting other mechanisms of IRF5-mediated growth inhibition, led us to examine the effect of IRF5 on tumor cell metastasis/invasion." (PMID 22053985, 2011). "IRF5 is an important tumor suppressor that regulates multiple cellular processes involved in the conversion of normal mammary epithelial cells to tumor epithelial cells with metastatic potential." (PMID 22053985, 2011). "Results presented here provide the first clear support of IRF5 tumor suppressor function and identify a new role for IRF5 in tumor cell invasion/metastasis." (PMID 22053985, 2011). "Further support for IRF5 in regulating tumor metastasis was obtained by examining IRF5 expression in clinical metastatic lymph node tissues from IDC patients." (PMID 22053985, 2011). "To determine how IRF5 inhibited outgrowth, we examined expression of genes contained in a pre-designed Human Tumor Metastasis PCR array." (PMID 22053985, 2011). "These vesicles influence the pre-metastatic microenvironment by suppressing immune evasion mechanisms and decreasing metastatic colonization, particularly in the lungs, highlighting IRF5 critical role in reducing tumor metastasis and improving patient survival." (PMID 40103824, 2025). "In recent years, IRF5 has emerged as a focus of tumor research." (PMID 41179282, 2025). "The monocytic MDSC subpopulation was higher in the IRF5 low tumor bearing mice at early stages of tumor growth in both the OS and BC models, indicating a subpopulation of MDSC that may be implicated in metastatic growth from IRF5 loss." (PMID 38969706, 2024). "Collectively, our engineered IRF5 M1‐exos represents a promising strategy for tumor immunotherapy." (PMID 39623605, 2024). "Furthermore, immunohistochemical experiments conducted on transplanted tumor models in nude mice confirmed significantly elevated levels of HLA‐E expression in tumor tissues from the IRF5 M1‐exos group compared to the M1‐exos group." (PMID 39623605, 2024). "Indeed, when the hydrogels were injected into mice tumor tissue, a sustained release of the nanoparticle complex was observed, which upregulated IRF5 expression and down-regulated CCL5 expression in tumors." (PMID 37587290, 2024). "Moreover, our experiments using a nude mouse model revealed that IRF5 M1‐exos exerted potent therapeutic effects by effectively suppressing tumor growth." (PMID 39623605, 2024).